GNAS (GNAS complex locus)
Diseases named in the same sentence as GNAS in open-access papers (continued):
Sharing a sentence is not in itself a finding about the gene and the disease.
acromegaly (continued). "Mutations in GNAS are present as somatic mutations in up to 40% of sporadic somatotroph adenomas and as mosaic mutations in McCune-Albright syndrome, a genetic disorder characterized by skin and bone manifestations as well as increased incidence of acromegaly." (PMID 36545335, 2022). "GNAS genes and proteins, functioning as transducers in numerous signaling pathways controlled by G protein-coupled receptors, and known to mutate in several somatotroph adenomas, were higher expressed in FCA." (PMID 33066652, 2020). "Clinical characteristics of acromegaly patients in relation to the status of GNAS gene in different genders." (PMID 39513543, 2025). "Recent advances have spotlighted the role of molecular mechanisms, identifying mutations in the α-subunit of stimulatory guanine nucleotide-binding protein (GNAS) gene as the foremost drivers of acromegaly." (PMID 39513543, 2025). "Hotspot variants in GNAS and USP8 are the most common genetic causes of acromegaly and Cushing’s disease, respectively." (PMID 38067388, 2023). "GNAS variant can be responsible for somatotroph hyperplasia involving the entire pituitary gland, with or without development of a somatotroph adenoma." (PMID 40078582, 2025). "Clinical characteristics of acromegaly patients in relation to the presence or absence of somatic GNAS mutation." (PMID 39513543, 2025). "Our observations that MEG3 activation in somatotroph cells due to an activating GNAS mutation, concomitantly the inactivation of Wnt/β-catenin pathway and inhibition of EMT may explain distinctive somatotroph adenoma features." (PMID 38827318, 2024). "Pegvisomant is also an effective treatment option for acromegaly in patients with MAS; however, whether GNAS mutation influences treatment outcome between different available therapies is not known." (PMID 36545335, 2022). "Transcriptomic group 1 includes ~20% of acromegaly patients with GNAS mutations-negative, mainly densely granulated tumors that co-express GIPR and NR5A1 (SF-1)." (PMID 36497102, 2022). "Sporadic gain-of-function mutations of the GNAS gene coding for the Gsα protein occur in approximately 40% of somatotroph tumors causing acromegaly; however, there are no systemic data on the presence of the GNAS mutations in silent somatotroph tumors." (PMID 29275530, 2018). "However, without genetic studies on gene mutations (e.g., AIP, PRKAR1A, GPR101, GNAS, MEN1, CDKN1B, SDHx, MAX, it is difficult to assess whether OL-23/77 was affected by gigantism and acromegaly or just one of these diseases." (PMID 35498425, 2022). "GNAS mutational status could not provide a complete explanation of the clinical characteristics of acromegaly; however, proteomics analysis showed that GNAS-MT influenced the expression of many proteins, including those involved in the GPCR pathway." (PMID 36435867, 2022). "Thus, the CNVs in GNAS mutation-negative somatotroph adenomas provide an alternative tumorigenic pathway, which is linked to genomic instability." (PMID 33574795, 2020). "Point mutations in GNAS and other genomic and nongenomic aberrations in the tightly regulated GHRH-GHRHR signaling pathway result in persistent cAMP signaling, inducing GH production and somatotroph proliferation, and potentially favoring the development of sporadic somatotroph adenomas." (PMID 41824769, 2026).
pituitary adenomas (19 papers, 2013 to 2026). "Intriguingly, a recent study introduced another viewpoint, proposing that GNAS mutation and GNAS copy number gain were mutually exclusive events in pituitary adenomas." (PMID 39513543, 2025). "We obtained DNA from frozen pituitary adenomas to screen for GNAS hotspot mutations and assessed the associated clinical characteristics." (PMID 39513543, 2025). "GNAS mutations were proposed to be involved in the constitutive activation of cAMP, which plays a causal role in pituitary adenomas." (PMID 38827318, 2024). "In fact, the most frequent somatic mutation associated with pituitary adenomas is a gain of function mutation of GNAS." (PMID 39194755, 2024). "Approximately 30%–40% of growth hormone–secreting pituitary adenomas (GHPAs) harbor somatic activating mutations in GNAS (α subunit of stimulatory G protein)." (PMID 38827318, 2024). "GNAS is a known oncogene that was first described in growth hormone-secreting pituitary adenomas and has been found to be mutated in some cancers." (PMID 35141142, 2021). "Somatic GNAS mutations are frequently encountered in pituitary adenomas and in patients with intraductal papillary mucinous neoplasm of the pancreas." (PMID 32127014, 2020). "In the case of Patient 12, who was diagnosed with a pituitary adenoma, GNAS mutation (p.Arg201Cys) was detected in this tissue by Sanger sequencing but not in peripheral blood leukocytes by both Sanger sequencing and MEMO-PCR." (PMID 27506760, 2016). "Rare causes of hyperthyroidism are: activating mutations in TSHR or GNAS genes, pituitary adenomas, differentiated thyroid cancer or gestational trophoblastic disease; congenital hyperthyroidism cases are also seen, although less frequently than CH." (PMID 25908941, 2015). "GNAS mutations have been reported in several neoplasms in the endocrine system, some pituitary adenomas, and in McCune–Albright syndrome." (PMID 24897499, 2014). "GNAS mutations have also been identified in several tumours of the endocrine system, some pituitary adenomas, and in McCune–Albright syndrome." (PMID 24897499, 2014). "Prevalence: Roughly 30–40% of GH-secreting pituitary adenomas possess a somatic GNAS mutation." (PMID 39194755, 2024). "Dysregulation of the G signaling can be implicated in various cancers, thus causing mutations in the guanine nucleotide binding protein and alpha stimulating (GNAS) gene encoding for the Gs alpha subunit, which is commonly associated with cancers: pituitary adenomas, ovarian, and pancreatic tumors." (PMID 39452927, 2024). "In addition, frequent GNAS mutations were reported in pituitary adenomas, colorectal villous adenomas and pyloric gland adenomas." (PMID 24312577, 2013). "It is of interest that GNAS mutations were frequently detected in benign tumors such as colorectal villous adenoma (83%), appendiceal low- grade mucinous neoplasm (50%), pyloric gland adenoma (63%), inflammatory type hepatocellular adenoma (5%) and pituitary adenoma (40%)." (PMID 24312577, 2013). "c.602G > A (p.Arg201His) in GNAS was detected in two patients in blood, and c.601C > T (p.Arg201Cys) in GNAS was detected in one patient in pituitary adenoma." (PMID 27506760, 2016). "The lack of phenotype-genotype correlation between GNAS-mutated and non-mutated pituitary adenomas could be explained by modulation of phosphodiesterase enzymes responsible for the hydrolysis of cyclic adenosine monophosphate." (PMID 29947650, 2018). "The present study evaluated clinical, laboratory, and GNAS, AIP, and PTTG molecular data of 62 apparently sporadic pituitary adenomas followed in a single endocrine tertiary-referral center." (PMID 29947650, 2018).
somatotropinomas (19 papers, 2014 to 2025). "Most studies suggest that GNAS mutations are associated with dense somatotrophic tumors, and the efficacy of first-generation SSA is higher." (PMID 40149642, 2025). "While wild-type somatotropinomas often display relaxation of the paternal imprinting, this phenomenon is infrequent in tumors carrying GNAS variants." (PMID 38067388, 2023). "At the molecular level, GNAS hotspot variants define a distinctive subgroup of somatotropinomas that display hypomethylation, limited chromosomal alterations, and activation of the GPCR pathway, although results vary among studies." (PMID 38067388, 2023). "In both sporadic and MAS-related somatotropinomas, GNAS variants almost always affect the maternal allele." (PMID 38067388, 2023). "Although GNAS mutations are the most prevalent cause of somatotroph tumors, the cause of half of all pathogenesis occurrences remains unclarified." (PMID 36010855, 2022). "Forty percent of somatotroph tumors harbor recurrent activating GNAS mutations, historically called the gsp oncogene." (PMID 34299200, 2021). "Twelve of the top 15 genes across all PitNETs were mitochondrially encoded enzymes and the three other genes encoded for two of the pituitary hormones GH and PRL, and the G protein GNAS, mutated in up to 50% of sporadic somatotroph tumors." (PMID 34758873, 2021). "These 2 groups were specifically associated with functional characteristics, and with GNAS mutation status in somatotroph tumors." (PMID 33168091, 2020). "GNAS gain-of-function mutations have been identified in 30% of somatotropinomas and USP8 or USP48 mutations in about 40% of corticotroph PitNETs." (PMID 33168091, 2020). "The most common recurrent somatic mutations occur in GNAS in somatotroph tumors, and in USP8 in corticotroph tumors." (PMID 32201880, 2020). "GNAS (p.Q227L, n=1; p.Q227R, n=1 and p.R201C, n=9) somatic missense mutations were found in heterozygosis in 11/41 patients with somatotropinomas (27%) and in 1/21 (p.R201C) with NFPA (4.8%) (P=0.05)." (PMID 29947650, 2018). "In line with previous results, GNAS proto-oncogene-activating mutations were the most frequent genetic mutation identified in 27 and 4.8% of somatotropinomas and NFPA, respectively." (PMID 29947650, 2018). "Many G proteins have been linked to tumor development, starting with the discovery that somatic gain-of-function mutations of codons 201 and 227 in the GNAS gene are responsible in one third of the sporadic somatotropinomas with elevated cAMP levels." (PMID 25291362, 2014). "The stimulatory guanine nucleotide (GTP) binding protein alpha (GNAS; encoding Gαs subunit) has been found to be mutated in 30–40% of sporadic somatotropinomas." (PMID 25291362, 2014). "In most cases, somatotropinomas result from somatic mutations in the GNAS gene." (PMID 40149642, 2025). "The clinical consequences of GNAS variants have been thoroughly studied in somatotropinomas." (PMID 38067388, 2023). "The most common cause of somatotroph tumors is somatic mutations in the GNAS gene, 20q13.3." (PMID 36010855, 2022). "Although 40% of somatotroph tumors are caused by somatic mutations in the Guanine nucleotide activating subunit (GNAS) gene and the additional portion can be explained by the handful of classified rare germline mutations, the cause of almost half of all somatotroph tumors remains unclarified." (PMID 36010855, 2022). "However, other studies associated the presence of GNAS mutation with smaller (in diameter) and less invasive somatotropinomas (18, –20)." (PMID 29947650, 2018). "So far, few genes have been identified as drivers for PitNETs, such as GNAS in somatotroph tumors and USP8 in corticotroph tumors." (PMID 40523964, 2025). "Genetic analysis revealed that 27% of somatotropinomas and 4.8% of NFPA harbored GNAS mutations (P=0.05)." (PMID 29947650, 2018).
somatotropinomas (continued). "In this study, we assessed the presence of GNAS and AIP mutations as well as altered gene expressions of AIP and PTTG in sporadic somatotropinomas and NFPA patients admitted to a single endocrine tertiary-referral center." (PMID 29947650, 2018). "Most PitNETs are without known mutations, with some exceptions: GNAS (somatotroph tumors), USP8 (corticotroph tumors), and ATRX (corticotroph tumors)." (PMID 39388031, 2024). "While somatic mutations of GNAS are the most prevalent cause of somatotroph tumors, germline mutations in various genes (AIP, PRKAR1A, GPR101, GNAS, MEN1, CDKN1B, SDHx, MAX) are also known as the cause of somatotroph tumors." (PMID 36010855, 2022). "These GIPR-expressing somatotropinomas are negative for GNAS mutations." (PMID 32201880, 2020).
mucinous neoplasm (17 papers, 2013 to 2025). "KRAS and GNAS mutations, which are frequently observed in pancreatic and appendix mucinous neoplasms, have been documented to be positive in some cases of PRMC." (PMID 41002570, 2025). "Only six lesions were classified as non-mucinous; however, two of them showed mutations in KRAS and GNAS, recategorizing these lesions as mucinous neoplasms, which led to a modification of the follow-up plan." (PMID 41464573, 2025). "Previous research has indicated a pooled sensitivity for mutated GNAS in PCF of 46% (39–56%) in mucinous neoplasms and 56% (45–66%) in IPMN through DNA-targeted sequencing." (PMID 40622417, 2025). "The prevalence of pathogenic KRAS or GNAS variants is high in mucinous neoplasm (approximately 2/3 of mucinous neoplasms contain a pathogenic variant of either KRAS, GNAS or both 38), making KRAS and GNAS variants reliable molecular markers." (PMID 33536452, 2021). "Although this could indicate tumor progression of the peritoneal metastasis, the presence of both KRAS and GNAS mutations in particular point towards peritoneal metastasis of a primary mucinous tumor of the appendix or pancreas." (PMID 32711552, 2020). "However, one study showed that low-grade mucinous neoplasms were associated with concurrent KRAS proto-oncogene, GTPase (KRAS), and GNAS complex locus (GNAS) mutations." (PMID 37566041, 2023). "More recently, it has been reported that intraductal papillary neoplasms of the bile duct, pyloric gland adenoma of the stomach and duodenum, and low grade appendiceal mucinous neoplasms resembled IPMN histologically and that these neoplasms had a high frequency of GNAS mutations." (PMID 24897499, 2014). "However, Singhi and colleagues showed that GNAS is commonly mutated in both low-grade and high-grade disseminated appendiceal mucinous neoplasms, suggesting that GNAS mutation status is not related to the grade of appendiceal mucinous neoplasms." (PMID 33712927, 2021).
lung carcinoma (16 papers, 2018 to 2025). "The expressions of GAPDH in colon cancer, PTMA in healthy control, and GNAS in non–small-cell lung cancer were also higher." (PMID 35770000, 2022). "Based from the results, we have noted low specificities for certain genes and cancer types including GRB10 gene for lung cancer and GNAS gene for thyroid cancers." (PMID 32448196, 2020). "The GAPDH gene was more stable in colon cancer, and the GNAS gene was highly stable in lung cancer." (PMID 35770000, 2022). "Based on the elevated BAE, MAE and TE signatures observed for various cancers over benign lesions, we formulated a statistical malignancy prediction model and identified GNAS, GRB10 and SNRPN as effective diagnostic biomarkers in ten different cancer types, including lung cancer." (PMID 34906185, 2021). "Among all the tested genes, the top-performing ones were NUMA1 and JAK1 in KIRC, PDGFRB and BCL6 in lung cancer, IRS2 in endometrial cancer, and GNAS in BRCA, each with an AUC of at least 0.89." (PMID 38491101, 2024). "A recent study identified aberrant allelic expression of both GNAS and HM13 at 20q11-13.32, as well as that of imprinted GRB10 at 7p12.1 and SNRPN 15q11.2 as useful biomarkers for lung cancer diagnosis." (PMID 36461044, 2022). "Notable ORFs enriched in metastatic tissues include GNAS and MYC, which were previously shown to promote KRAS-driven lung cancer metastasis." (PMID 30013058, 2018). "Studies have shown that YAP1 expression is induced by KRAS activation, aerobic glycolysis, GNAS, and the cancer upregulated gene (CUG) 2 exhibiting upregulated expression in lung cancer which could increase the expression of YAP1." (PMID 33648545, 2021). "Of these fusions, 16 (including ALK, ARAF, BRAF, FGFR1, FGFR3, RET, and ROS1) and 21 (including ABL1, GNAS, JAK2, and NRG1) were classified as either related to lung cancer, or as oncogenes that have not been reported in lung cancer, respectively." (PMID 36153311, 2022).
Cushing syndrome (15 papers, 2017 to 2025). Cushing's syndrome (CS) encompasses a group of hormonal disorders caused by prolonged and high exposure levels to glucocorticoids that can be of either endogenous (adrenal cortex production) or exogenous (iatrogenic) origin. "On the other hand, GNAS mutations can also contribute to Cushing’s-like syndrome since they are associated with various endocrine disorders, including certain subtypes of Cushing’s syndrome, such as McCune-Albright syndrome." (PMID 39502570, 2024). "Mutations in PRKACA (the PRKACB paralogue) and GNAS are mutually exclusive in Cushing’s syndrome and result in similarly sized adrenocortical adenoma diameter and similar increases in serum cortisol." (PMID 39342354, 2024). "Examining GNAS mutations could help physicians detect extra-adrenal malignancies, which may contribute to an improved prognosis for patients with this type of Cushing’s syndrome." (PMID 30670014, 2019). "Here, we describe the first case of subclinical Cushing’s syndrome represented by autonomous cortisol secretion and paradoxical response to oral dexamethasone administration, harboring an activating mutation in the α subunit of the stimulatory G protein (GNAS)." (PMID 30670014, 2019). "Benign adrenal cortical tumors presenting with Cushing syndrome often have diverse mutations (PRKACA, PRKAR1A, GNAS, PDE11A, and PDE8B) involving the cyclic AMP signaling pathway." (PMID 29594118, 2018). "We describe a case of subclinical Cushing’s syndrome (SCS) with autonomous cortisol secreting adrenal tumor, who showed this paradoxical reaction due to harboring an activating mutation in the α subunit of the somatic stimulatory G protein (GNAS)." (PMID 30670014, 2019). "CPA is the result of abnormal differentiation from ZF cells and is usually caused by somatic mutations of protein kinase cAMP-activated catalytic subunit alpha (PRKACA), GNAS complex locus (GNAS) and catenin beta 1 (CTNNB1), resulting in hypercortisolism and clinical Cushing’s syndrome." (PMID 34943980, 2021).